ADGRD2 (adhesion G protein-coupled receptor D2)
Description:
Orphan receptor.
Synonyms: GPR144; PGR24
Target class: Family B G protein-coupled receptor; Membrane receptor
Gene: Protein-coding gene on chromosome 9 (124,450,451 to 124,478,589, forward strand). Ensembl gene ENSG00000180264.
Subcellular location: Membrane
Homologues: Orthologues: macaque ADGRD2 (88% identical), chimpanzee ADGRD2 (87% identical), pig ADGRD2 (70% identical), rabbit ADGRD2 (62% identical), guinea pig ADGRD2 (54% identical), tropical clawed frog adgrd2 (39% identical), zebrafish adgrd2 (35% identical). Paralogues in human: ADGRF5 (17% identical), ADGRG6 (16% identical), ADGRG4 (16% identical), ADGRD1 (15% identical), ADGRL3 (15% identical), ADGRF3 (15% identical), ADGRF1 (15% identical), ADGRL2 (14% identical), ADGRB1 (14% identical), ADGRL1 (14% identical), ADGRB2 (13% identical), ADGRB3 (13% identical), and 30 more.
Diseases named in the same sentence as ADGRD2 in open-access papers:
ADGRD2 is named in the same sentence as 7 diseases in open-access papers, as found by Europe PMC text mining. Sharing a sentence is not in itself a finding about the gene and the disease. The quoted sentences say what the papers report.
osteosarcoma (2 papers, 2022 to 2024). A usually aggressive malignant bone-forming mesenchymal neoplasm, predominantly affecting adolescents and young adults. "For the first time, GPR144 (ADGRD2) has been linked to the prognosis of osteosarcoma." (PMID 38586328, 2024). "GPR144 (ADGRD2) was an important mediator in the hypoxic response of glioblastoma and had a significant tumor-promoting effect, associated with rheumatoid factor and osteosarcoma proliferation and invasion." (PMID 35463319, 2022).
ADGRD2 also shares sentences with these, for which no sentence is quoted: tumor (2 papers); congenital heart defects (1); endometriosis (1); glioblastoma (1); metabolic syndrome (1); neurodevelopmental disorder (1).